IL1B (interleukin 1 beta)
Diseases named in the same sentence as IL1B in open-access papers (continued):
Sharing a sentence is not in itself a finding about the gene and the disease.
type 2 diabetes (continued). "Among them, TNFα and IL-1b are two cytokines known to be upregulated in type 2 diabetic patients, which have demonstrated in vitro and in vivo animal models the ability to reduce the functional expression of the cardiac repolarizing current Ito." (PMID 34202017, 2021). "Here, we demonstrated the role of two of them, TNFα and IL-1b, in the cardiac electrical remodeling of type 2 diabetes." (PMID 34202017, 2021). "In humans and rodent models, IL-1β is tied to the pancreatic β cell dysfunction of type II diabetes through the effect of IL-1β to inhibit glucose-stimulated insulin secretion." (PMID 34944138, 2021). "IL-1β triggers endoplasmic reticulum stress, which is involved in the pathogenesis of type 2 diabetes." (PMID 33535473, 2021). "Studies have indicated that the level of proinflammatory cytokines, IL-1β and IL-6, descended significantly in inflammatory bowel disease 39, acute pancreatitis 40 and type 2 diabetes 17 after injection of HUMSCs." (PMID 32210708, 2020). "TXNIP activates the NLRP3 inflammasome and subsequent secretion of IL-1β in the pathogenesis of type 2 diabetes." (PMID 32842536, 2020). "Regarding type 2 diabetes, only when basal levels of IL-1β mRNA are low, hyperglycemia induced IL-1β production in β cells can be observed." (PMID 32477265, 2020). "Cytokines such as IL-1β are upregulated in pancreatic islets of patients with type 2 diabetes and regulate numerous other cytokines and chemokines, consequently increasing its production in β cells, engendering a vicious cycle." (PMID 33293987, 2020). "Conversely, BMAL1 is severely depleted in islets from patients with type 2 diabetes (T2D) and disrupted by IL-1β exposure of islets in vitro." (PMID 32650582, 2020). "NLRP3 is an inflammasome protein that once activated leads to the processing of IL1β, a cytokine involved in the pathology of type 2 diabetes." (PMID 31164864, 2019). "Spironolactone treatment reduced the activation of caspase-1 and mature IL-1β content in arteries taken from mice with type 2 diabetes." (PMID 31817997, 2019). "There was a weak correlation between the elevated mtDNA levels and IL-1β levels in plasma from patients with type 2 diabetes." (PMID 30965677, 2019). "We analyzed caspase-1 activation and the IL-1β and IL-18 secretion in lipopolysaccharide (LPS)-primed bone marrow-derived macrophages (BMDMs) stimulated with ccf-DNA from patients with type 2 diabetes and poly(dA:dT), an AIM2 inflammasome activator." (PMID 30965677, 2019). "Elevated NLRP3, ASC, IL-1β gene expression, and protein levels are observed in macrophages obtained from untreated type 2 diabetic patients." (PMID 31197747, 2019). "While IL-1β, glucagon and Apo-B are individual markers for type 2 diabetes, PDGF-BB, IL-13, eotaxin, Apo-E, and Apo-CII are the individual markers for the CAD group." (PMID 30674322, 2019). "Children who presented within 6 h of coma onset had higher concentrations of IL-1β, IL-6, and IL-10 than those who presented more than 18 h after coma onset." (PMID 30477519, 2018). "In epidemiologic studies, a variety of circulating inflammatory markers, such as IL-1β, have been identified as strong predictors of type 2 diabetes." (PMID 29850615, 2018). "Increased inflammasome activation and IL-1β production of PBMCs have been described in insulin-resistant patients with type 2 diabetes and in newly diagnosed type 1 diabetes." (PMID 30483253, 2018). "Overexpression of IL-6 and IL-1β in periodontally inflamed tissue has also been postulated as a mechanism by which type 2 diabetes enhances periodontal destruction." (PMID 29075409, 2017). "IL-1β vaccine was shown to be also effective in a type 2 diabetes model, and its human counterpart was well tolerated in a phase I clinical trial in patients with type 2 diabetes." (PMID 28197099, 2017).
type 2 diabetes (continued). "In particular, the IL-1β is thought to play a predominant role in the development of several age-related degenerative diseases including type 2 diabetes and Alzheimer’s Disease (AD)." (PMID 28790890, 2017). "This study aims to assess the proinflammatory interleukin 1β (IL-1β) and anti-inflammatory IL-10 production by monocytes from 38 patients with type 2 diabetes and 31 controls in different glucose concentrations." (PMID 29225725, 2017). "Inflammasome activation and subsequent IL-1β production is a driver of islet pathology in type 2 diabetes." (PMID 28500395, 2017). "A similar positive response on glycemic control was established using an anti-IL-1β antibody in type 2 diabetes." (PMID 28109186, 2017). "During the past three decades, a large number of studies have documented a role of IL-1β in type 1 and type 2 diabetes." (PMID 28109186, 2017). "Islet macrophage infiltration and expression of inflammasome components and pro-IL-1β are increased in type 2 diabetes." (PMID 28500395, 2017). "The importance of IL-1β in the development of type 2 diabetes is supported by several in vitro, in vivo, and clinical studies." (PMID 28463985, 2017). "Inflammatory cytokines, including IL-1β, inhibit insulin-dependent glucose uptake and are increasingly recognized to play an important role in insulin-resistance in the pathogenesis of type 2 diabetes." (PMID 27438413, 2016). "IL-1β is an cardinal proinflammatory cytokine, which governs the outcome of renal disease, and moreover, inhibition of IL-1β can ameliorate type 2 diabetes." (PMID 25834832, 2015). "IL-1β also plays a vital role in initiating and maintaining inflammation-induced organ dysfunction in type 2 diabetes mellitus (T2DM)." (PMID 26136779, 2015). "In particular, interleukin-1β (IL-1β) has been involved in the pathogenesis of type 1 and type 2 diabetes, as well as in the development of the diabetic retinopathy associated to type 1 diabetes." (PMID 25518980, 2014). "In the framework of this model, an IL-1β switch is sufficient and necessary to account for type 2 diabetes onset." (PMID 25167060, 2014). "In a follow-up study, a synergistic elevation in circulating levels of IL-1β and IL-6 was suggested to be predictive of type 2 diabetes." (PMID 24918199, 2014). "Type 2 diabetes appears to be an example of an auto-inflammatory disease where glucose induces IL-1β production from the insulin-producing beta cell and IL-1β induces the beta cell to produce its own IL-1β." (PMID 23847614, 2013). "IL-1β is emerging as a therapeutic target in several inflammatory conditions, including type 2 diabetes." (PMID 23460908, 2013). "Randomized clinical trials have shown that the blockade of IL-1β signaling by anakinra, a recombinant human IL-1 receptor antagonist, reduced systemic inflammation and improved glycemia of type 2 diabetes (134, –136)." (PMID 23964268, 2013). "A number of recent landmark studies have pointed out a key role for an excessive NLRP3 inflammasome activation in the IL-1β-related development of type 2 diabetes." (PMID 23843683, 2013). "In humans, elevated plasma levels of IL-1β have been found to be predictive of type 2 diabetes, and clinical studies have suggested that treatment with the IL-1β receptor antagonist anakinra has beneficial effects in type 2 diabetic patients." (PMID 23843683, 2013). "In a GK rat model of type 2 diabetes, treatment with IL-1 receptor antagonist (IL-1Ra) reduced islet mRNA expression of a number of inflammatory factors which includes: IL-1β, IL-6, TNF-α, MCP-1 and MIP-1α." (PMID 24359406, 2013). "Administration of neutralizing monoclonal antibodies to IL1β improved glycemic control and beta cell function in type 2 diabetic patients." (PMID 23941335, 2013). "Systemic levels of proinflammatory cytokines, including TNF-α, IL-1β, and IL-6, are elevated in patients with both type 1 and type 2 diabetes." (PMID 23320034, 2012).
type 2 diabetes (continued). "Exposure of human islets to glucose, leptin, or free fatty acids (FFA) increases the production and release of IL-1β, hence, therapy targeting IL-1β is a logical choice in protecting the beta-cell in type 2 diabetes." (PMID 22922276, 2012). "The NLRP3 inflammasome activation promotes kidney injury process with up-regulation of IL-1β and IL-18 and enhances IL-1β levels in the type 2 diabetes." (PMID 22701621, 2012). "Recent positive clinical results from a small trial with high affinity anti-human IL-1β (XOMA 052) also support targeting IL-1β mediated inflammatory damage to pancreatic beta cells as a potential therapeutic approach for type 2 diabetes." (PMID 21410952, 2011). "Cytokines including IL-1β, leptin, resistin, and adiponectin have been shown to play important roles in the development of pancreatic β-cell dysfunction and type 2 diabetes." (PMID 21113299, 2010). "As beta cell dysfunction and death in type 2 diabetes has been associated with cytokine-induced radical formation, we incubated INS-1 cells, rat islets and P. obesus islets with IL-1β and measured free radical formation, beta cell function and beta cell death." (PMID 20948968, 2010). "IL-1β-mediated pancreatic β-cell dysfunction and apoptosis are involved in the pathogenesis of pancreatic β-cell dysfunction and type 2 diabetes." (PMID 21113299, 2010). "Although an initial analysis suggested a significant positive correlation between IL-1β concentrations in plasma and tears in patients with type 2 diabetes, this association did not remain significant after adjustment for multiple testing." (PMID 41030257, 2025). "Il1α, together with Il1β, belongs to the interleukin-1 family, which has been much more studied in the context of metabolic diseases, and its inhibition is one of the pharmacological strategies being tested as a treatment for type 2 diabetes." (PMID 40426854, 2025). "Additionally, the induction of β-cell death by IL-1β, is known to contribute to the onset and progression of type 2 diabetes." (PMID 40332318, 2025). "In this context, our study demonstrated that treatment of type 2 diabetic rats with FA for 28 days significantly downregulated hepatic and renal levels of key pro-inflammatory mediators – including NF-κB-p65, IL-1β, and IL-6 – compared to untreated diabetic rats." (PMID 41142063, 2025). "Individuals with type 2 diabetes are prone to fatigue, which can be improved by inhibiting IL-1β." (PMID 39496966, 2025). "Indeed, islets from individuals with type 2 diabetes fail to respond to IL-1β with insulin secretion, whereas islets from healthy donors are reactive to IL-1β." (PMID 39496966, 2025). "Since IL-1β and IL-6 levels are increased in type 2 diabetes and are primarily released from adipose tissue and visceral fat, it can be hypothesized that these pro-inflammatory cytokines may support the accumulation of MDSCs in adipose tissue." (PMID 39518420, 2024). "IL-1β is also a prominent pro-inflammatory cytokine whose aberrant expression and regulation drives disease progression in different chronic inflammatory conditions, such as type 2 diabetes, and chronic inflammation involving skin and bone." (PMID 39591258, 2024). "Therapeutics against IL-1β show promise for treating type 2 diabetes." (PMID 39606781, 2024). "These researchers concluded “that targeting cytokines, cytokine receptors, and inflammation-associated nuclear transcription factors, such as IL-1β, IL-αR, TNF-α, and NF-kB alone or in combination, can significantly reduce the level of FPG, HbA1c, and CRP in patients with type-2 diabetes." (PMID 39199336, 2024). "Its activation induces the maturation and secretion of the pro-inflammatory factors IL-1β and IL-18, and studies have shown that NLRP3 activation is associated with the pathogenesis of a variety of diseases, including gout, type 2 diabetes mellitus, and Alzheimer’s disease." (PMID 39202931, 2024).
type 2 diabetes (continued). "Moreover, the increased production of IL-18 and IL-1β mediated by inflammasomes contributes to the onset and progression of RA, type II diabetes, and various neurodegenerative disorders, including Alzheimer’s disease (AD) and ALS51." (PMID 38036728, 2023). "Further studies could be conducted to profile blood-derived macrophages and their IL-1β secretion levels in type 2 diabetes patients being treated with empagliflozin to explore a potential correlation." (PMID 36902218, 2023). "IL-1β is reported to inhibit insulin signaling; randomized clinical trials shows that blocking IL-1β signaling (using recombinant human IL-1 receptor antagonist) is effective in type 2 diabetes." (PMID 36741414, 2022). "And the IL-1β vaccine also improved glucose tolerance in diet-induced type 2 diabetes." (PMID 36405706, 2022). "An interesting study by Liao reported that a db/db type 2 diabetes mouse model that displayed obvious mechanical allodynia was associated with the activation of spinal astrocytes but not microglia by the “Astrocyte-IL-1β-NMDAR-Neuron” pathway." (PMID 35115925, 2021). "Indeed, several recent reports have shown that long-chain FAs, such as palmitate, induce IL1β signaling and mediate the pro-inflammatory response in type 2 diabetes." (PMID 34198548, 2021). "However, more recently, IL-1β has also been suggested to have a role in RA comorbidities such as type 2 diabetes and cardiovascular disease." (PMID 33605409, 2021). "IL‐1β is also known to activate macrophages in the pancreas leading to β‐cell dysfunction and death, explaining a link between chronic elevation of IL‐1β signalling and type 2 diabetes." (PMID 33363732, 2020). "After 30 days of treatment, B. vernae extract significantly decreased the serum levels of fasting blood glucose, insulin, insulin resistance index, glycated serum protein, TNF-α, IL-1β, and IL-6, whereas significantly increased the serum levels of insulin sensitivity index in type 2 diabetic rats." (PMID 32636751, 2020). "Importantly, inflammasome activation is observed in circulating cells and adipose tissue of patients with insulin resistance, and plasma concentrations of IL-1β and IL-18 are elevated in patients with type 2 diabetes and predict development of this disease." (PMID 32968070, 2020). "In human monocytes, CASP5 and CASP4 could be activated by saturated fatty acids, then trigger IL‐1β and IL‐18 release, which contributed to type 2 diabetes." (PMID 32311223, 2020). "Type 2 diabetes (T2DM) and its complications are associated with a systemic low-grade inflammation manifested by higher systemic levels of proinflammatory cytokines, such as IL-6, IL-1β, or TNFα." (PMID 30983877, 2019). "Moreover, we show that the IL-1β levels were elevated in the plasma from patients with type 2 diabetes." (PMID 30965677, 2019). "Consistently, the ccf-DNA (ccf-DNA #1 and ccf-DNA #2) from two independent patients with type 2 diabetes showed significantly higher IL-1β and IL-18 secretion in response to poly(dA:dT) as compared with the vehicle control, whereas the secretion of tumor necrosis factor (TNF)-α was unchanged." (PMID 30965677, 2019). "Next, we examined the elevated mtDNA levels to determine whether they correlated with the IL-1β levels in the plasma from patients with type 2 diabetes." (PMID 30965677, 2019). "Notably, the IL-1β levels were significantly higher in the plasma from patients with type 2 diabetes (T2D) compared to healthy subjects (control)." (PMID 30965677, 2019). "Moreover, our results suggest that ccf-mtDNA regulates IL-1β levels in patients with type 2 diabetes." (PMID 30965677, 2019). "Pro-inflammatory molecules (e.g., TNF, IL-6, IL-1β) are increased in type II diabetes and AD, which may compromise the hippocampal insulin receptor expression and/or signaling." (PMID 31291963, 2019). "In addition, our results show that the IL-1β levels were increased in plasma from patients with type 2 diabetes." (PMID 30965677, 2019).
type 2 diabetes (continued). "In addition, NLRP3 inflammasome activation and production of IL-1β are upregulated in the peripheral mononuclear cells of drug-naïve type-2 diabetic patients, suggesting a role of the inflammasome in the pathogenesis of type-2 diabetes." (PMID 30404221, 2018). "Chronic exposure of islets to the inflammatory cytokines interleukin-1 beta (IL-1β), tumor necrosis factor-alpha (TNF-α) and interferon-gamma (IFN-γ) is associated with β-cell destruction and decreased secretory parameters in both Type 1 and Type 2 Diabetes." (PMID 28893192, 2017). "Because PA induces secretion of IL-6 from macrophages and our data demonstrates PA induces secretion of IL-1β from human MoDCs, it is possible to suggest that PA may exacerbate the development of type 2 diabetes through stimulation of innate immune cells." (PMID 28463985, 2017). "For example, enhancement of AMPK activity was shown to cause suppression of palmitate-induced inflammasomes activation, whereas deficiency of AMPK by a pharmacological inhibitor or siRNA enhanced IL-1β and IL-18 production in monocyte-derived macrophages from patients with type 2 diabetes." (PMID 28617316, 2017). "The role of IL-1β in type 2 diabetes was demonstrated by clinical trials using the recombinant IL-1 receptor antagonist anakinra: it improved glycaemic control in individuals with type 2 diabetes and improved inflammation and beta cell function for months after therapy cessation." (PMID 28500395, 2017). "Also, IL1B is reported to stimulate the synthesis and release of NPY which also contribute to induction of type-II diabetes in susceptible subjects." (PMID 27749914, 2016). "IL-1β is an important factor in the pathogenesis of type 2 diabetes." (PMID 26694746, 2015). "In a clinical trial exploring the role of IL-1β in type II diabetes disease progression, in which patients received IL-1Ra (s.c) once daily for 13 weeks, an improvement in insulin production and glycemic control was observed, along with a reduction in the inflammatory biomarkers, CRP and IL-6." (PMID 25705177, 2015). "We found that IgG from Hispanics with type 2 diabetes neutralized the secretion of IL-1β from DCs." (PMID 26633920, 2015). "In addition, type-2 diabetic patients and mice fed a high-fat diet demonstrate IL-1β production following inflammasome activation from obesity-induced danger signals." (PMID 23843683, 2013). "Besides, the cleavage of caspase-1 and release of mature IL-1β were significantly elevated in monocyte-derived macrophages from type 2 diabetic patients compared with controls." (PMID 23843683, 2013). "Here, we outline the new immunological mechanisms that link metabolic dysfunction to the emergence of chronic inflammation and discuss the opportunities and challenges of future therapeutic approaches to dampen NLRP3 inflammasome activation or IL-1β signaling for controlling type 2 diabetes." (PMID 23483669, 2013). "For example, after disruption of the BBB plasma derived molecules known to prime IL-1β responses such as minimally oxidized LDL, and which are associated with co-morbid diseases like type II diabetes, could prime glia at the lesion site." (PMID 23024646, 2012). "IL-1β is produced in different tissues, not only as a response to pathogens, but also as a danger signals in pathologies such as acute myocardial infarction, type 2 diabetes, neural disorders." (PMID 22467443, 2012). "IL-1β is involved in WNV-induced Langerhans cell migration from the skin to draining lymph nodes in the mice model, and also plays a critical role in the pathogenesis of type 2 diabetes and its associated complications." (PMID 22953001, 2012). "Consistent with our data, a recent study also reported that IL-1β overexpression could be blocked by intrathecally administered LAA in a type 2 diabetes-induced neuropathic pain." (PMID 21969850, 2011). "In support, IL-1β expression is shown to be increased in islets from type 2 diabetic patients." (PMID 21113299, 2010).